KDM3A (lysine demethylase 3A)
Diseases named in the same sentence as KDM3A in open-access papers (continued):
Sharing a sentence is not in itself a finding about the gene and the disease.
Ewing sarcoma (12 papers, 2015 to 2025). A small round cell tumor that lacks morphologic, immunohistochemical, and electron microscopic evidence of neuroectodermal differentiation. "Our studies identified a role for KDM3A in Ewing Sarcoma, and subsequently RMS, and demonstrated efficacy of the pan-JHDM inhibitor JIB-04, in both cancer types." (PMID 39448867, 2025). "KDM3A (a H3K9me1/2 demethylase) is highly overexpressed by Ewing sarcoma cells and promotes pro-metastatic and migratory gene expression." (PMID 36505823, 2022). "Based on this research, KDM3A was then suggested as a candidate therapeutic target for Ewing Sarcoma treatment." (PMID 35590288, 2022). "Their following study in 2017 further demonstrated that KDM3A positively regulated metastasis-related genes in Ewing Sarcoma." (PMID 35590288, 2022). "For instance, KDM3A has been identified as a new miR-22-targeted gene, and its expression can be inhibited by miR-22, thus preventing Ewing sarcoma clonogenic and anchorage-independent cell growth." (PMID 32092824, 2020). "MCAM has previously been identified as a prevalently overexpressed cell surface protein in pediatric cancers, and our own prior studies demonstrated it to be an important mediator of KDM3A effects in Ewing Sarcoma." (PMID 32577157, 2020). "In mechanistic studies, we demonstrate that both RMS subtypes utilize a KDM3A/Ets1/MCAM disease-promoting axis recently discovered in Ewing Sarcoma, another aggressive pediatric cancer of distinct cellular and molecular origin." (PMID 32577157, 2020). "In previous studies, our group demonstrated disease-promoting properties for the Jumonji-domain histone demethylase (JHDM) KDM3A in Ewing sarcoma, as well as pre-clinical efficacy of a pan-JHDM inhibitor in this disease." (PMID 33196691, 2020). "Specifically, we showed that, in Ewing Sarcoma, an aggressive pediatric cancer of bone and soft tissue, KDM3A acts as both a tumor promoter, and, through its downstream-induced gene MCAM, a promoter of metastasis." (PMID 32577157, 2020). "We noted Ets1 expression to be dramatically higher in RMS cell lines relative to Ewing Sarcoma A673 cells, in which we had originally identified Ets1 as an important component of the KDM3A/Ets1/MCAM disease-promoting axis." (PMID 32577157, 2020). "Our previous studies in Ewing Sarcoma showed that KDM3A positively controls the expression of Ets1, and that KDM3A and Ets1 both control expression of MCAM." (PMID 32577157, 2020). "Similarly, KDM2B was upregulated in Ewing sarcoma and correlated with worse prognosis, and KDM3A was also found to promote the migration in vitro and metastasis in vivo of Ewing sarcoma." (PMID 39766049, 2024). "However, compared to the known effect of KDM3A in Ewing Sarcoma, less is known regarding its function in the more common type of bone tumor OS." (PMID 35590288, 2022). "Compared to its oncogenic role in Ewing Sarcoma, less is known about the function of KDM3A in OS." (PMID 35590288, 2022). "Interestingly, KDM3A has been reported to epigenetically activate melanoma cell adhesion molecules to promote migration and metastasis of Ewing Sarcoma, the second most frequent solid pediatric tumor of bone and soft tissue." (PMID 35590288, 2022). "However, our prior studies in Ewing Sarcoma also demonstrated KDM3A localization to the Ets1 and MCAM promoter regions, while our current analogous studies in FP-RMS did not." (PMID 32577157, 2020). "Furthermore, similar to our prior studies in Ewing's sarcoma (ES), we identified the Ets1 transcription factor as an important downstream contributor to KDM3A regulation of the disease‐promoting gene MCAM." (PMID 32697014, 2020). "Our previous studies identified a new regulatory axis with growth and metastasis promotional properties, involving KDM3A, Ets1 and MCAM, in Ewing Sarcoma." (PMID 32577157, 2020). "This revealed 34 genes commonly upregulated by KDM3A (down with KDM3A knockdown) in FN-RMS RD cells, FP-RMS Rh30 cells, and Ewing Sarcoma A673 cells." (PMID 32577157, 2020).
Ewing sarcoma (continued). "KDM3A is highly expressed in the FN-RMS lines RD and SMS-CTR, and the FP-RMS lines Rh30 and Rh41, at levels similar Ewing Sarcoma (A673 cells shown as a reference;)." (PMID 32577157, 2020). "In summary, we show that the KDM3A/Ets1/MCAM molecular axis, which we have previously demonstrated to manifest tumor and metastasis promotional properties in Ewing Sarcoma, also plays potent disease-promoting roles in both FN-RMS and FP-RMS." (PMID 32577157, 2020). "KDM3A and MCAM each present potential new therapeutic targets in both subtypes of RMS, similar to our previous findings in Ewing Sarcoma." (PMID 32577157, 2020). "KDM3A is up-regulated in Ewing sarcoma and this is at least in part as a result of EWSR1-Fli1 expression, which appears to act by repressing miR-22 and in turn de-repressing KDM3A." (PMID 26204834, 2015). "Since, miR-22 was reported to target and regulate KDM3A in Ewing sarcoma, these findings suggest that miR-22 may regulate both PHF8 and KDM3A in LNCaP cells, at steady state as well as in the presence of CS-FBS or IL-6." (PMID 27689328, 2016). "Due to the reliance of EWS::FLI1 on chromatin remodeling complexes, there is great interest in targeting Ewing sarcoma and the fusion specifically using epigenetic drugs including agents that inhibit HDACs (HDACi), bromodomain proteins (BETi), LSD1 (LSD1i), and KDM3A (JIB-04)." (PMID 36505823, 2022). "Thus, in contrast to our previous findings in Ewing Sarcoma, KDM3A does not appear to control Ets1 and MCAM expression via direct association with proximal regulatory elements in FP-RMS." (PMID 32577157, 2020).
male infertility (12 papers, 2010 to 2024). The inability of the male to effect fertilization of an ovum after a specified period of unprotected intercourse. "HSP90AB1 interacted with the catalytic domain of Kdm3a, that mutant Kdm3a can cause male infertility in mice." (PMID 34580317, 2021). "Further molecular genetics studies are required to be carried out in order to practically confirm the association of the KDM3A gene with male infertility." (PMID 30053768, 2019). "A few single-gene defects that cause male infertility have been identified in humans, but the function and performance of the KDM3A gene in humans is still unclear." (PMID 30053768, 2019). "The aim of this study was to screen any new mutation in KDM3A gene to explore more details of human male infertility." (PMID 30053768, 2019). "This miRNA was predicted to target and regulate a specific H3K9 demethylase (lysine-specific demethylase 3A: KDM3A) with a proven role in male infertility in animal models." (PMID 39876905, 2024). "The mentioned study revealed hsa-mir-27a-3p was overexpressed in NOA patients; it targeted the KDM3A transcript and consequently led to male infertility." (PMID 35911855, 2022). "Also, both Kdm3a-mutant and Kdm3a-depleted mice display male infertility and impaired spermatogenesis with smaller testis sizes and decreased sperm count, indicating that KDM3A plays a key role in adult testes." (PMID 38926399, 2024). "Some previous human and animal studies have supported the idea that KDM3A down-regulation might be the main cause of male infertility, especially in non-obstructive azoospermia (NOA)." (PMID 35911855, 2022). "Consequently, downstream genes which are controlled by KDM3A such as PRM1 and TNP1 are not expressed and all these together drive to male infertility in NOA men." (PMID 33349804, 2020).
bladder cancer (11 papers, 2016 to 2024). "KDM3A was found to regulate the growth of bladder cancer cells and HOXA1 expression through the demethylation of H3K9me2." (PMID 37627900, 2023). "The mRNA expression levels of HOXA1 and KDM3A were significantly higher in bladder cancer tissues as compared to normal bladder tissues." (PMID 37627900, 2023). "On the other hand, KDM3A downregulation decreases bladder cancer proliferation, in vitro colony formation, and in vivo xenograft tumor growth." (PMID 32354028, 2020). "KDM3A has been reported to demethylate H3K9me2 on the promoter of glycolytic gene PGK, and it cooperated with HIF-1α to induce aerobic glycolysis in urinary bladder cancer." (PMID 35590288, 2022). "Strikingly, KDM3A and HOXA1 exhibit strong correlations in bladder cancer tissues (n = 55) and cell lines (n = 18), further supporting that KDM3A contributes to bladder cancer progression by regulating HOXA1." (PMID 32354028, 2020). "Of note, histone demethylase KDM3A, also termed as JMJD1A, has been found to be upregulated in bladder cancer and lung adenocarcinoma while knockdown of KDM3A possesses therapeutic potential." (PMID 33520978, 2020). "Recently, KDM3A, a demethylase that removes methyl form histone lysine H3K9, has been reported to promote urinary bladder cancer progression by enhancing glycolysis through coactivation of hypoxia inducible factor 1α." (PMID 31931846, 2020). "As a result, KDM3A promotes bladder cancer progression by enhancing glycolysis via coactivating HIF-1α and may serve as a potential target for bladder cancer treatment." (PMID 32354028, 2020). "KDM3A expression is significantly higher in human bladder cancer cell lines and tissues than in nontumor bladder tissues." (PMID 32354028, 2020).
ovarian carcinoma (11 papers, 2017 to 2021). A malignant neoplasm originating from the surface ovarian epithelium. "Another KDM, KDM3A, is overexpressed in various ovarian cancer tissues, and its expression was significantly elevated in three cisplatin resistant ovarian cancer cell lines, compared to normal ovarian tissue." (PMID 33669182, 2021). "High expression of KDM3A facilitates ovarian cancer growth and survival, as its depletion leads to G2/M cell cycle arrest, senescence, and apoptosis." (PMID 32354028, 2020). "Upregulation of KDM3A in platinum-resistant ovarian cancer contributes to ovarian cancer stemness and chemoresistance." (PMID 32354028, 2020). "KDM3A is crucial for the ovarian cancer cells to successfully progress through the critical stages of tumor progression such as cell proliferation, maintenance of CSCs and development of chemoresistance." (PMID 30064416, 2018). "Recently, two KDMs, KDM3A in ovarian cancer and KDM5A in glioblastoma, were shown to confer resistance to chemotherapy." (PMID 29360266, 2018). "KDM3A and Sox2 expressions were significantly elevated in ovarian cancer than the adjacent normal tissues." (PMID 27694900, 2017). "Consistently, KDM3A depletion inhibited the growth of subcutaneously implanted cisplatin-resistant human ovarian cancer cells in athymic nude mice." (PMID 27694900, 2017). "Taken together, these results clearly indicated that KDM3A is required for the cell growth and confers chemoresistance in ovarian cancer." (PMID 27694900, 2017). "Next, to identify the molecular mechanism of KDM3A-mediated ovarian cancer stemness, we assessed the expression of stem cell pluripotent markers such as Sox2, Oct4, Nanog and Lin28 by real-time RT-PCR." (PMID 27694900, 2017). "In view of our finding, we attempted to analyze the patient data sets from oncomine database to identify the correlation between KDM3A expression and cisplatin resistance in ovarian cancer." (PMID 27694900, 2017). "Consistently, KDM3A depletion inhibited in vivo growth of ovarian cancer xenograft in mice and abundantly expressed in human ovarian cancer tissues." (PMID 27694900, 2017). "In brief, our findings reveal a novel mechanism by which KDM3A promotes ovarian CSCs, proliferation and chemoresistance and thus, highlights the significance of KDM3A as a novel therapeutic target for resistant ovarian cancer." (PMID 27694900, 2017). "Here we identified that lysine demethylase KDM3A as a critical regulator of ovarian cancer stemness and cisplatin resistance by inducing the expressions of pluripotent molecules Sox2 and Nanog and anti-apoptotic B-cell lymphoma 2 (Bcl-2), respectively." (PMID 27694900, 2017). "To understand the functional role of KDM3A in resistant ovarian cancer, we stably knocked down KDM3A by lentiviral method in OVCAR-5/CDDP and A2780/CDDP cells by using two shRNAs targeting different sequences on KDM3A mRNA." (PMID 27694900, 2017). "Altogether, these results indicated that KDM3A is required to maintain CSCs population in ovarian cancer." (PMID 27694900, 2017). "Knockdown of KDM3A induced cell cycle arrest, promoted cellular senescence and apoptosis in platinum-resistant ovarian cancer cells." (PMID 27694900, 2017). "In addition to in vitro results, KDM3A depletion also significantly hampers ovarian cancer growth in vivo." (PMID 32354028, 2020). "Furthermore, KDM3A contributes to ovarian cancer stemness in cisplatin-resistant cells through the regulation of pluripotent proteins such as Sox2, Nanog, Oct4, and Lin28." (PMID 32354028, 2020). "Therefore, small molecules or drugs targeting KDM3A represent potential therapeutics for treating chemoresistant ovarian cancer." (PMID 32354028, 2020).
ovarian carcinoma (continued). "Moreover, KDM3A and Sox2 expression are both increased in ovarian cancer than in the normal tissues, and their expression is positively correlated with each other." (PMID 32354028, 2020). "Therefore, KDM3A epigenetically activates Sox2 expression and promotes ovarian cancer stemness by removing repressive histone marks." (PMID 32354028, 2020). "Therefore, we next sought to determine the importance of KDM3A for in vivo growth of human ovarian cancer by utilizing the mouse tumor xenograft model." (PMID 27694900, 2017). "Interestingly, KDM3A depletion led to G2/M cell cycle arrest, which was accompanied by increased apoptosis, indicating that KDM3A is crucial for ovarian cancer cell proliferation and survival." (PMID 27694900, 2017). "Further, to check whether the high abundance of KDM3A correlated with platinum resistance in other ovarian cancer cells, we determined the KDM3A protein expression in parental and platinum-resistant SKOV3 and A2780 cells." (PMID 27694900, 2017). "Because our findings indicated that high abundance of KDM3A coincide with cancer stemness and chemoresistance in ovarian cancer, we hypothesized that KDM3A might be a critical regulator of CSCs in ovarian cancer." (PMID 27694900, 2017). "Significant amount of KDM3A protein was detected on Sox2 promoter and KDM3A knockdown reduced KDM3A occupancy with concomitant increase in H3K9me2, indicating that KDM3A may epigenetically activates Sox2 expression to promote ovarian cancer stemness." (PMID 27694900, 2017). "The findings presented here demonstrated for the first time that histone demethylase, KDM3A is crucial for the ovarian cancer cells to successfully progress through the critical stages of tumor progression such as cell proliferation, maintenance of CSCs and development of chemoresistance." (PMID 27694900, 2017). "Moreover, the abundance of KDM3A was positively correlated with Sox2 levels, indicating the functional significance of KDM3A in human ovarian cancer." (PMID 27694900, 2017). "In addition, KDM3A induces ovarian cancer growth while antagonizing cellular senescence by repressing the expression of cyclin-dependent kinase inhibitor, p21Waf1/Cip1." (PMID 27694900, 2017). "Moreover, KDM3A is abundantly expressed and positively correlated with Sox2 expression in human ovarian cancer tissues." (PMID 27694900, 2017). "Altogether, these results indicated that KDM3A might be a crucial epigenetic factor required for platinum resistance in ovarian cancer." (PMID 27694900, 2017). "Taken together, these observations suggest that KDM3A might play a key role in ovarian cancer growth and survival." (PMID 27694900, 2017). "To gain the molecular insight into the mechanism by which KDM3A regulates ovarian cancer growth and chemoresistance, we screened the expression of key cell cycle and apoptotic regulatory proteins in scrambled control and KDM3A knockdown OVCAR-5/CDDP cells by immunoblot." (PMID 27694900, 2017). "Notably, all the cisplatin-resistant ovarian cancer cells consistently overexpressed KDM3A protein as compared with parental cell line." (PMID 27694900, 2017). "To further determine whether KDM3A epigenetically activates Sox2 expression to control ovarian cancer progression, we determined KDM3A and Sox2 protein expression in human ovarian cancer tissue array containing primary and metastatic ovarian cancer and adjacent normal tissues." (PMID 27694900, 2017). "Indeed, KDM3A depletion significantly inhibited the ovarian cancer growth in vivo." (PMID 27694900, 2017). "Indeed, both OVCAR-5/CDDP and A2780/CDDP cells expressing KDM3A shRNAs showed high abundance of senescence-associated β-galactosidase positive cells as compared with scrambled control cells, indicating that KDM3A prevents the cellular senescence to promote sustained growth of ovarian cancer." (PMID 27694900, 2017).
ovarian carcinoma (continued). "Since the demethylating activity and biological functions of KDM3A resides in the catalytic subunit, it can be a potential druggable target for small molecules that specifically target the rigid catalytic domain and thus can be exploited to device a novel therapy to target-resistant ovarian cancer." (PMID 27694900, 2017). "Conversely, NO has been found to inhibit lysine demethylase 3A (KDM3A), a histone demethylase that is known to positively regulate cancer cell invasion, chemoresistance and metastasis in breast and ovarian cancer cells." (PMID 30082427, 2018). "We identified that lysine demethylase KDM3A/JMJD1A, which specifically demethylates H3K9me2, is highly expressed in platinum-resistant ovarian cancer cells." (PMID 27694900, 2017). "Although in-depth investigations in ovarian cancer have not been conducted, KDM3A is induced >1.7-fold in hypoxic SKOV3ip.1 cells." (PMID 27869162, 2017). "In this regard, our results indicating KDM3A as a key epigenetic factor controlling ovarian CSCs may offer a new perspective to develop an inhibitor that specifically target KDM3A to eliminate CSC population and overcome chemoresistance in ovarian cancer." (PMID 27694900, 2017).